RN7SL318P (RNA, 7SL, cytoplasmic 318, pseudogene)
Gene: Miscellaneous RNA gene on chromosome 8 (5,142,411 to 5,142,707, reverse strand). Ensembl gene ENSG00000242079.
Homologues: Orthologues: chimpanzee Metazoa_SRP (99% identical), macaque Metazoa_SRP (88% identical). Paralogues in human: RN7SL1 (78% identical), RN7SL2 (78% identical), RN7SL122P (78% identical), RN7SL126P (78% identical), RN7SL709P (78% identical), RN7SL3 (77% identical), RN7SL650P (77% identical), RN7SL597P (77% identical), RN7SL220P (77% identical), RN7SL45P (77% identical), RN7SL517P (76% identical), RN7SL296P (76% identical), and 703 more.